WWOX (WW domain containing oxidoreductase)
Diseases named in the same sentence as WWOX in open-access papers (continued):
Sharing a sentence is not in itself a finding about the gene and the disease.
tumor (continued). "While evodiamine exerts anti-tumor effects through inhibiting β-catenin activity, and WWOX regulates β-catenin accumulation in cytoplasm, the effects of evodiamine on the expression of WWOX are also still unknown." (PMID 28708106, 2017). "Other reports described adult epileptic patients homozygous for mutant WWOX but with no sign of tumor development, suggesting that other hits and/or mutations might be required for cancer to develop." (PMID 27977694, 2016). "In addition, we observed a reduced protein levels of WWOX and p21, an increased expression of Cyclin D1 by miR-153 overexpression, suggesting that miR-153 could also promote tumor growth in vivo." (PMID 25708809, 2015). "Therefore, we also evaluated the difference between the WWOX mRNA expression rates in the tumor samples carrying the G and T alleles but we did not observe any difference." (PMID 25612104, 2015). "Thus, our data indicate that WWOX does not behave as a classical highly penetrant tumor suppressor gene and more likely the loss of WWOX expression is related to tumor progression." (PMID 22574198, 2012). "The WW domain-containing oxidoreductase (WWOX) gene, well-known as a tumor suppressor, also has a crucial role as a transcription factor in the developing brain." (PMID 42193054, 2026). "The treatment increased levels of IFN-γ, CD8+ T cells, and antigen-presenting cells, while downregulating miR-29a-3p, a microRNA known to suppress the tumor suppressor WWOX in CRC and promote tumor progression." (PMID 41440025, 2025). "In addition, ITCH‐mediated ubiquitination can perform a tumor‐suppressive role via impaired degradation of WWOX, which may be due to the fact that most of the evidence accumulated to date on the role of ITCH in tumorigenesis has come from in vitro or in vitro models." (PMID 38342606, 2024). "WW domain-containing oxidoreductase (WWOX) was first isolated in 2000, and has been considered a candidate tumor suppressor protein." (PMID 38542478, 2024). "This also suggests that both WWOX and BRCA1 play crucial roles in maintaining the normal function of cellular processes, such as DNA integrity, that prevent tumor development." (PMID 38499540, 2024). "WWOX plays a crucial role in the choice of DSB repair pathway in mammary cells, highlighting its significance as a tumor suppressor in breast carcinogenesis." (PMID 38499540, 2024). "Collectively, our study demonstrates that WWOX intensifies apoptosis, suppresses proliferation and viability, diminishes adhesion to various ECM proteins, reduces tumor growth and the quantity of colonies, and reduces the invasiveness of GBM." (PMID 36979157, 2023). "Our study indicates that WWOX intensifies apoptosis, suppresses proliferation and viability, diminishes adhesion to various ECM proteins, reduces tumor growth and the quantity of colonies, and reduces the invasiveness of GBM." (PMID 36979157, 2023). "Currently, several potential biomarkers have been proposed, including levels of tumor proteins such as ASS1, HIF-1, and WWOX." (PMID 37445845, 2023). "To further examine the tumor suppressor function of WWOX in human PDXs, we used CRISPR/Cas9 to knockout WWOX in PDX114, which expresses high levels of WWOX, and assessed its effects on colony formation." (PMID 36572673, 2022). "WWOX and FHIT are tumor inhibitor genes located in common chromosomal fragile sites FRA3B and FRA16D, respectively." (PMID 35250573, 2022). "The transcriptional regulator WW domain-containing oxidoreductase (WWOX) is a key player in a number of cellular and biological processes including tumor suppression." (PMID 33916893, 2021). "One of the genes affecting both cytoskeleton and GBM is WW domain-containing oxidoreductase (WWOX), a haploinsufficient tumor suppressor described in many cancers, including GBM, for which it impairs malignant phenotype." (PMID 34204789, 2021).
tumor (continued). "Decreased WWOX expression in GDM compared to normal pregnancy, and in particular reduction of WWOX/HIF1A ratio, indicate that WWOX modulates HIF1α activity in normal tissues as described in the tumor." (PMID 33520443, 2021). "It has been shown that the interplay of WWOX and TFAP2A/TFAP2C affects the biology of the tumor thus corresponding bioinformatics analyses involving BLCA cohort were performed as a follow-up of in vitro experiments." (PMID 33691672, 2021). "The significance of such enrichment reaches p < 10−58 for CACNA1C and SNX29 from the Network of Cancer Genes, and p < 10−61 for WWOX and CSMD1 from the Tumor Suppressor Gene Database." (PMID 33741065, 2021). "In accordance with cell line results expression of the WWOX, DVL-1, DVL-2 and DVL-3 genes were lower (73.5 %, 51%, 56.1% and 50%) in the tumor tissues and the differences were statistically significant." (PMID 32368285, 2020). "Although levels of WWOX expression varied among tumor samples included in this analysis, this may be attributed, in part to differences in the heterogeneity of tumor stroma, presence other inflammatory cells within the tumor microenvironment, and/or normal structures within the epidermis and dermis." (PMID 33129329, 2020). "Some of the tumor suppressors and oncogenes regulated by HNRNPA2B1 include c-FLIP, BIN1, and WWOX, and the proto-oncogene RON." (PMID 33163396, 2020). "The target of miRNA-134 was identified as WW domain-containing oxidoreductase (WWOX), a tumor suppressor that is part of the family of WW domain-containing proteins." (PMID 30901831, 2019). "Human and mouse WW domain-containing oxidoreductase, designated WWOX, FOR, or WOX1, has been generally regarded as a tumor suppressor since its discovery in 2000." (PMID 30158849, 2018). "The preceding observations demonstrated that WWOX inactivation coupled with DEN treatment and HFD intake leads to enhanced proliferation and tumor formation." (PMID 29724996, 2018). "Numerous studies of human tumor cells have shown that FSs can be connected with frequent breakage and rearrangements, e.g., FRA16D harboring the WWOX gene." (PMID 28884345, 2018). "Enforced expression of TMEM207 abrogated the binding of WWOX to HIF‐1α, increased HIF‐1α and GLUT‐1 expression, even under normoxic conditions, and promoted tumour growth in a xenoplant assay using SAS tongue squamous cancer cells." (PMID 29164763, 2018). "They further described that upon binding, WWOX translocates to the VOPP1-containing lysosomal compartment and proposed that VOPP1 behaves as a negative regulator of WWOX tumor suppressor activity via this protein-protein sequestration mechanism." (PMID 30619736, 2018). "While previous studies indicated that evodiamine exerts anti-tumor effects through inhibiting β-catenin activity, and WW domain-containing oxidoreductase (WWOX) regulates β-catenin accumulation in cytoplasm, the effects of evodiamine on the expression of WWOX are still unknown." (PMID 28708106, 2017). "Our findings presented here and previous observations argue that WWOX, gene products of FRA16D, functions as a tumor suppressor." (PMID 26675548, 2016). "Cumulatively, these observations indicate that the gene product of FRA16D, WWOX, behaves as a tumor suppressor by affecting several signaling pathways and promoting efficient DDR." (PMID 27977694, 2016). "WW domain containing oxidoreductase (WWOX) gene, which is also located in these regions is considered an important role in tumor suppression through transcriptional repression and apoptosis." (PMID 27501229, 2016).
tumor (continued). "Q-values determined by reanalysis of the GISTIC database identified several CFS-Gs in this category, including WWOX (1.24E-265), LRP1B (1.85E-196), PARK2 (1.02E-149), and FHIT (8.70E-72), emphasizing their significant roles as tumor suppressors." (PMID 27977694, 2016). "WWOX and FHIT have long been known to reside at common fragile sites and have been demonstrated to act as suppressors of tumor development by gene knockout mouse models." (PMID 26375816, 2015). "Functional analysis revealed that miR-134 expression enhanced the oncogenicity of HNSCC cells in vitro as well as tumor growth and metastasis of HNSCC cells in vivo via targeting WW domain-containing oxidoreductase (WWOX)." (PMID 26504785, 2015). "The WWOX gene is located at a common fragile region (FRA16D) and behaves as a tumor suppressor gene." (PMID 25612104, 2015). "WW-domain-containing oxidoreductase (WWOX) is the tumour suppressor gene from the common fragile site FRA16D, whose altered expression has been observed in tumours of various origins." (PMID 24938873, 2014). "The tumor suppressor genes assessed were fragile histidine triad (FHIT), WW domain-containing oxidoreductase (WWOX), fused in sarcoma-1 (FUS1) and phosphatase and tensin homolog (PTEN)." (PMID 25024751, 2014). "Human WW domain-containing oxidoreductase (WWOX, FOR, or WOX1) induces apoptosis, probably via the mitochondrial pathway and is a proapoptotic protein and a tumour suppressor." (PMID 24949445, 2014). "Cell lines data enabled the identification of patients among which, despite high expression of WWOX tumor suppressor, no advantageous outcomes were noted due to the cancer-promoting profile ensured by other genes." (PMID 37781246, 2023). "Three tumor suppressor genes residing on the most active sites of this type are Fragile Histidine Triad Diadenosine Triphosphatase (FHIT) at FRA3B, WW Domain Containing Oxidoreductase (WWOX) at FRA16D and Parkinson Disease-2 (PARK2) at FRA6E." (PMID 34204827, 2021). "Together, these results provide a molecular basis for the non-classical tumour suppressor functions of WWOX and the better prognosis observed in cancer patients with higher levels of WWOX activity." (PMID 34210081, 2021). "Tax-mediated activation of the noncanonical pathway suppresses the expression of the WWOX (WW domain containing oxidoreductase) tumor suppressor gene, which inhibits canonical NF-κB signaling." (PMID 32645846, 2020). "Given the lack of complete patient information and follow-up accompanying the archival canine tumor samples, it was not possible to determine the prognostic significance of WWOX immunoreactivity in canine MCTs." (PMID 33129329, 2020). "Recurrent SVs in CSMD1, WWOX, ERC1, PDE4D and SHANK2 were also identified in five tumor samples." (PMID 32617189, 2020). "In the present study, we also analyzed the expression levels of the WWOX gene in 98 HNSCC tumor tissues and adjacent non-cancerous tissue samples." (PMID 32368285, 2020). "In the subgroup analysis of TNM stages, low WWOX expression patients showed significantly shorter OS and RFS in TNM I‐II subgroup, while WWOX expression failed to predict tumor outcomes in the TNM III‐IV subgroup." (PMID 29905011, 2018). "It has become clear from multiple studies that WWOX (WW domain-containing oxidoreductase) operates as a “non-classical” tumor suppressor of significant relevance in cancer progression." (PMID 30619736, 2018). "While multiple mechanisms have been suggested to explain the tumor suppressive role of WWOX, there is currently no functional evidence for the exact role of WWOX in breast carcinogenesis." (PMID 30082886, 2018). "This positive correlation suggests that the absence of FRA16D breakage within the WWOX tumor suppressor is accompanied by elevated PARTICLE expression." (PMID 29152092, 2017).
tumor (continued). "The expression level of WWOX in IA tissues was significantly lower than that in corresponding normal tissues (P = 0.004), and the deletion genotypes of CNV-67048 have lower WWOX mRNA levels in both tumor tissues and border tissues (P < 0.01)." (PMID 26910372, 2016). "In order to determine the level of WWOX expression in HNSCC tumors, we performed quantitative analysis using real-time RT-PCR, in a cohort of 80 tumor samples and compared these with the expression levels in the adjacent non-cancerous tissue samples from the same patient." (PMID 25612104, 2015). "Although its normal role in vivo and functional contribution to cancer have not been fully defined, WWOX does have an integral role in metabolism and can suppress tumor growth." (PMID 26302329, 2015). "In this study we investigated the WWOX messenger RNA expression levels in association with the promoter methylation of the WWOX gene and miR-134 expression levels in 80 HNSCC tumor and non-cancerous tissue samples." (PMID 25612104, 2015). "Present knowledge of WWOX function suggests that, contrary to initial assumptions, it does not act as a classical tumor suppressor." (PMID 25051421, 2014). "Our previous report showed that WWOX may be involved in GBM carcinogenesis and/or tumor progression." (PMID 25051421, 2014). "Some studies in mice with conditional Wwox deletion, however, did not support the categorization of WWOX as a primary tumor suppressor gene since no spontaneous neoplasms were observed." (PMID 24456803, 2014). "Our results also suggest that WWOX does not behave as classical tumour suppressor gene and its influence on cell functioning is more global and complicated." (PMID 24938873, 2014). "In this regard, the enforced expression of miR-29 in lung cancer cell lines led to reduced global DNA methylation, induced re-expression of methylation-silenced tumor suppressor genes, such as FHIT and WWOX, and inhibited tumor cell proliferation in vitro and tumor growth in vivo." (PMID 24275848, 2013). "By promoting the downregulation of the DNA methyltransferases 3A and B (DNMT3A and 3B), miR-29 induces re-expression of methylation-silenced tumor suppressor genes, such as the fragile histidine triad protein (FHIT) and the WW domain containing oxidoreductase (WWOX)." (PMID 24275848, 2013). "While the molecular function of WWOX is not known, it has been shown that the growth of tumor cells lacking WWOX is strongly inhibited by restoring WWOX expression." (PMID 22615583, 2012). "Non-canonical NF-κB also facilitates canonical NF-κB activation by repressing transcription of the WW domain-containing oxidoreductase (wwox) tumor suppressor gene, a specific inhibitor of Tax-induced RelA phosphorylation." (PMID 21743832, 2011). "Tumour and growth factor genes like WWOX, p73, ITGB4 and AREG were strongly up-regulated by PAR2 activation, supporting roles for PAR2 in proliferation, tumour growth and, perhaps surprisingly, also tumour suppression." (PMID 21072196, 2010). "WWOX, the gene that spans the second most common human chromosomal fragile site, FRA16D, is inactivated in multiple human cancers and behaves as a suppressor of tumor growth." (PMID 19936220, 2009). "This study describes the value of an innovative approach using an MLPA assay specifically designed to scan the exon intragenic composition of the FHIT and WWOX genes involved at fragile sites, here evaluated in the setting of ESCC South African cell lines and primary tumor specimens." (PMID 16895604, 2006). "Six tumor specimens showed an amplification profile comparable to that of the mean reference control with no significant exon deletions of FHIT or WWOX, (results not shown)." (PMID 16895604, 2006).
tumor (continued). "Human newborns lacking the WWOX gene and functional WWOX protein suffer severe neural diseases but do not have spontaneous tumor formation, suggesting WWOX does not fit Knudson’s two-hit hypothesis of tumorigenesis." (PMID 38542478, 2024). "Notably, 2 CpG sites located in the gene body region of tumor suppressor genes, namely LRIG1 (leucine-rich repeats and immunoglobulin-like domains 1, cg26131019) and WWOX (WW domain–containing oxidoreductase, cg02171206), were among the associated loci in the unstratified analysis." (PMID 37930698, 2023). "Suppression of pS14-WWOX by a small peptide Zfra (zinc finger-like protein that regulates apoptosis) leads to inhibition of cancer growth and blocking of AD progression, suggesting that WWOX is not an authentic tumor suppressor." (PMID 35883580, 2022). "Thus the role of WWOX in cancer is probably more prominent as a relevant gene in tumor progression rather than tumor initiation." (PMID 33946771, 2021). "The WWOX gene is a non-classical tumor suppressor located at the second most active CFS: FRA16D." (PMID 33718178, 2021). "At the end point of tumor growth experiments, Zfra significantly suppressed the expression of Hyal-2 and phosphorylation of WWOX at Y33 and Y61 (>90%), but no significant changes were observed for WWOX phosphorylation at S14 and Y287 in the spleen of the sacrificed mice (<5%)." (PMID 32764489, 2020). "Notably, many cell lines survive following stable transfection of WWOX; therefore, apoptosis would not be the only mechanism by which WWOX works as a tumor suppressor." (PMID 30285739, 2018). "However, no direct in vivo evidence linking WWOX tumor suppressor function with HCC development is known so far." (PMID 29724996, 2018). "Although the tumor suppressor property of WWOX is inarguable, WWOX is not inactivated in the manner characteristic of the canonical Knudson hypothesis." (PMID 30214895, 2018). "Interestingly, some of them function as tumor suppressors (e.g. BCL2L11, MXD1, WWOX, BNIP3L, and DMTF1) or are candidate tumor suppressors having anti-proliferative properties and DNA repair abilities (e.g. LRRC2, RPA4, PPP6R1, SPEN, RAP1GAP and CISH) (see discussion section)." (PMID 26918450, 2016). "Further studies of WWOX function might shed light on the intriguing question of why one of the most unstable chromosomal regions in the genome, FRA16D, is evolutionarily conserved and harbors a tumor suppressor?" (PMID 27551470, 2015). "Growing evidence indicates that WWOX is not a classical tumor suppressor." (PMID 25051421, 2014). "Furthermore, it has also been reported that altered or absent WWOX expression may suppress the functional role of p73 in apoptosis, leading to an increased possibility of tumor occurrence." (PMID 24137446, 2013). "This was a consequence of the decreased activation of the tumor suppressor WW domain containing oxidoreductase (WWOX), due to the lack of (neuT-C1KO) or decreased (neuT-C3KO) deposition of C1qA molecules in the tumor microenvironment." (PMID 35203439, 2022). "WWOX does not seem to act as a highly penetrant classical tumor suppressor, and low levels of Wwox, rather than complete absence of Wwox, are often observed in tumors, indicating that the tumor suppressor function of Wwox does not fit Knudson’s two hit hypothesis of tumorigenesis." (PMID 28045433, 2017). "However, we found no in vivo evidence for nuclear localization of ectopic WWOX in the presence of ectopic TNFα expression, indicating that the tumor suppressive functions may not be at the level of detection or alternatively they may be mediated through cytoplasmic WWOX functions." (PMID 26302329, 2015). "Notably, similarly to its FRA3B/FHIT counterpart, the role of FRA16D/WWOX in cancer has been controversial, resulting in their categorisation by some as “non-classical” tumour suppressor genes." (PMID 34210081, 2021).